MYO7B (myosin VIIB)
Description:
Myosins are actin-based motor molecules with ATPase activity. Their highly divergent tails are presumed to bind to membranous compartments, which would be moved relative to actin filaments. As part of the intermicrovillar adhesion complex/IMAC plays a role in epithelial brush border differentiation, controlling microvilli organization and length. May link the complex to the actin core bundle of microvilli.
Tractability: Small molecule: a structure with a bound ligand is known. PROTAC: ubiquitination databases record sites on it.
Gene: Protein-coding gene on chromosome 2 (127,535,683 to 127,637,729, forward strand). Ensembl gene ENSG00000169994.
Subcellular location: Cytoplasm, cytoskeleton; Cell projection, microvillus
Gene Ontology:
Molecular function: protein binding; actin filament binding; ATP binding; cytoskeletal motor activity
Biological process: brush border assembly; actin filament-based movement; endocytosis; sensory organ development; sensory perception of sound
Cellular component: brush border; microvillus; stereocilia ankle link; actin cytoskeleton; apical cytoplasm; cytoskeleton; myosin complex
Genetic constraint (gnomAD): Loss-of-function variants: 205 observed, 240.75 expected, observed/expected ratio (o/e) 0.85, 90% interval 0.76 to 0.96. The upper end of that interval is the gene's LOEUF score, 0.96, which puts it in group 4 of 6, group 1 being the genes least tolerant of losing a copy. Missense variants: 2,682 observed, 2,753.1 expected, observed/expected ratio (o/e) 0.97, 90% interval 0.94 to 1.01. Synonymous variants: 1,178 observed, 1,138.3 expected, observed/expected ratio (o/e) 1.03, 90% interval 0.99 to 1.09.
Homologues: Orthologues: chimpanzee MYO7B (98% identical), macaque MYO7B (95% identical), dog MYO7B (86% identical), pig MYO7B (84% identical), rabbit MYO7B (84% identical), mouse Myo7b (81% identical), rat Myo7b (81% identical), tropical clawed frog myo7b (55% identical), zebrafish myo7ba (53% identical), zebrafish myo7bb (48% identical), Caenorhabditis elegans hum-6 (44% identical), Drosophila melanogaster Myo28B1 (39% identical). Paralogues in human: MYO7A (54% identical), MYO15A (27% identical), MYO10 (24% identical), MYH6 (21% identical), MYH7B (21% identical), MYH7 (21% identical), MYH3 (21% identical), MYH2 (20% identical), MYH4 (20% identical), MYH1 (20% identical), MYH13 (20% identical), MYH8 (20% identical), and 32 more.
Diseases named in the same sentence as MYO7B in open-access papers:
MYO7B is named in the same sentence as 3 diseases in open-access papers, as found by Europe PMC text mining. Sharing a sentence is not in itself a finding about the gene and the disease. The quoted sentences say what the papers report.
Parkinson disease (1 paper, 2023). A progressive degenerative disorder of the central nervous system characterized by loss of dopamine producing neurons in the substantia nigra and the presence of Lewy bodies in the substantia nigra and locus coeruleus. "Myosin-7B (MYO7B) is a critical endocytosis regulator in the cell-to-cell transmission of misfolded α-synuclein in Parkinson’s disease." (PMID 37691828, 2023). "Myosin-7B (MYO7B) could regulate the cell-to-cell transmission in Parkinson’s disease." (PMID 37691828, 2023).
MYO7B also shares sentences with these, for which no sentence is quoted: cervical adenocarcinoma (1 paper); cervical cancer (1).